RNU6-177P (RNA, U6 small nuclear 177, pseudogene)
Gene: Small nuclear RNA gene on chromosome 7 (128,627,172 to 128,627,275, forward strand). Ensembl gene ENSG00000223189.
Homologues: Orthologues: chimpanzee U6 (100% identical), macaque U6 (90% identical), pig U6 (81% identical), dog U6 (78% identical), pig U6 (77% identical). Paralogues in human: RNU6-1319P (98% identical), RNU6-241P (98% identical), RNU6-747P (98% identical), RNU6-1076P (97% identical), RNU6-1100P (97% identical), RNU6-1118P (97% identical), RNU6-1217P (97% identical), RNU6-355P (97% identical), RNU6-447P (97% identical), RNU6-785P (97% identical), RNU6-791P (97% identical), RNU6-860P (97% identical), and 1285 more.